ERBB2 (erb-b2 receptor tyrosine kinase 2)
Diseases named in the same sentence as ERBB2 in open-access papers (continued):
Sharing a sentence is not in itself a finding about the gene and the disease.
tumor (continued). "Interestingly the level of ERBB2 mRNA in the ascites of mice treated with EGFR inhibitor lapatinib was at least twice as high as in the patient's tumor." (PMID 30499260, 2019). "The deviation from the null hypothesis that a tumor with an ERBB2 amplicon composed of one segment is found independently in patients suffering from localized or advanced tumors was tested using the Fisher exact test and is rejected with two sided p = 0.0001." (PMID 31827209, 2019). "First, from the standpoint of tumor biology, what features generally define the genomic architecture of HER2+ tumors, with particular regard for large genomic rearrangements that may extend beyond the ERBB2 amplicon?" (PMID 30005627, 2018). "Targeted next-generation-sequencing (tNGS) and comparative genomic hybridization array (CGH) have been performed on fresh tumor biopsies of patients included in the MOSCATO-01 and ongoing MOSCATO-02 trials to administrate HER2 inhibitors in case of ERBB2 pathogenic mutation of amplification." (PMID 29515767, 2018). "We compared tumor and patient characteristics of ERBB2 mutant and wild-type cases." (PMID 29522538, 2018). "Furthermore, intravenous delivery of the selected siRNAs aiming to suppress the expression of ER/BCL2 and ER/ERBB2/EGFR groups of proteins led to a significant retardation in tumor growth in a 4T1-induced syngeneic mouse model." (PMID 29932151, 2018). "Use of lapatinib, a dual ERBB1 and ERBB2 inhibitor, reduced tumour growth in an orthotopic animal model, suggesting that it may be of benefit to a subset of TGCT patients." (PMID 29160922, 2018). "In rare cases, a combination of ERBB2 amplification with high mRNA and/or protein expression and the absence of other major genomic alterations might be necessary to implicate Her2 as a driver in an individual tumor." (PMID 28205537, 2017). "ERBB2 and ERBB3 overexpression, cooperation in neoplastic transformation and loss of ERBB3 preventing the progressive transformation of ERBB2-over expressing tumours reinforces ERBB3’s pivotal role in ERBB signalling." (PMID 28591206, 2017). "Those cells are highly active against tumor targets, which might allow lower doses of ErbB2-CAR CIK cells still assuring robust ErbB2-specific cytotoxic potential." (PMID 29029499, 2017). "Through an integrated analysis of 127 patients from three centers, we identified alterations of Her2 at the DNA, RNA and protein level, and demonstrate that Her2 relevance as a tumor driver likely may vary even within ERBB2 amplified cases." (PMID 28205537, 2017). "Also, increased SRC-dependent PEAK1 expression by blockade of ERBB2 expression activates tumour growth." (PMID 28871116, 2017). "In orthotopic xenograft models in NSG mice, repeated stereotactic injection of ErbB2-specific NK-92/5.28.z cells into the tumor area effectively inhibited tumor progression and resulted in a marked extension of survival, while parental NK-92 cells were ineffective." (PMID 28572802, 2017). "To this end, we examined stemness in erbB-2-overexpressing tumor-derived cells and cell lines." (PMID 28061785, 2017).
tumor (continued). "Despite this, sCNAphase was able to detect at least 12 copies of the pathologically relevant ERBB2 in HCC1954 and HCC2218 across the entire cohort of mixtures, highlighting the diagnostic potential of sCNAphase at even 5% tumor DNA." (PMID 27903916, 2017). "Indeed, p140Cap confers to ERBB2 transformed cells limited in vivo tumour growth ability and spontaneous lung metastasis formation." (PMID 28300085, 2017). "ERRα levels also correlated with expression of ErbB2, an indicator of aggressive tumor behavior." (PMID 28945747, 2017). "While these data confirm the connection between RTK inhibition and ultimate tumor prevention, the results also suggest that lapatinib may induce a broader impact on erbB-2/EGFR signaling beyond the canonical regulatory pathways." (PMID 28061785, 2017). "The results revealed that miR-1268b was associated significantly with cancer chemosensitivity and ERBB2 expression, but not with lymph node metastasis or tumor size." (PMID 29163776, 2017). "Altogether, the sum of these data argues that p140Cap may effectively decrease pathways related to the progression of ERBB2 tumours, contributing to increased patient survival." (PMID 28300085, 2017). "In about 25% of Erbb2 over expressing tumors (5/21), trastuzumab in combination with cetuximab resulted in a moderate antitumor effect in terms of reduction in tumor morphology and tumor cell proliferation with concomitant activation of cleaved caspase-3." (PMID 28473715, 2017). "In the TCGA cohort, 45/407 (11%) tumours harbored missense SNVs in ERBB2." (PMID 28205537, 2017). "However, because ERBB2 copy number is heterogenous in a tumor cell population, independent rearrangements occur repeatedly in each cell." (PMID 28211519, 2017). "Both Tc-ErbB2/Th-HA peptide antigens, conjugated to the surface of liposomes via aPam3CSSanchor, can induce potent antigen-specific immune responses in the majority of tumor-bearing mice and delay tumor growth in BALB/c mice model." (PMID 29045460, 2017). "The CAR used by Sung Hee Yoon at al. in a study in which CIK cells were redirected against ErBb2 tumor targets contained a different anti-ErbB2 antibody fragment but was also joined to the intracellular portions of CD28 and CD3ζ, as was the case for the CAR construct used in our study." (PMID 29029499, 2017). "In the present work, we show that, consistently with previous data obtained with biotinylated anti-EGFR antibodies, AvidinOX anchorage significantly enhances in vitro anti-tumor activity of biotinylated anti-ErbB2 antibodies Trastuzumab (bTrast) or Pertuzumab (bPert)." (PMID 28186982, 2017). "Thus, these experiments demonstrate that Blimp1 expression impairs ErbB2/p130Cas-dependent tumor growth in vivo, by affecting cell proliferation." (PMID 28442738, 2017). "Moreover, mRNA expression and SRCIN1 gene CN from 50 of the 200 ERBB2 amplified tumours were significantly correlated, giving a Pearson correlation of 0.77." (PMID 28300085, 2017). "Because reduction of ERBB2 promoted tumor apoptosis in gastrointestinal adenocarcinomas, we hypothesized that miR-193a-5p may also induce tumor apoptosis." (PMID 27203740, 2016). "The only ERBB2 variant (L755S) was observed in patient N°20 in the metastasis but not in the primary tumor." (PMID 27028851, 2016). "Similar results have been obtained in an oncogenic ErbB2 tumour model." (PMID 27611942, 2016). "Analogously, blockade of the canonical PI3K/AKT/mTOR pathway by small-molecule inhibitors elicits apoptosis in ErbB2-overexpressing tumour cells that become addicted also to PI3K signalling, as it conveys proliferation and survival signals downstream of ErbB2/3 receptors." (PMID 27255951, 2016). "Indeed, we found that co-expression of Irs4 and ErbB2 in mammary epithelial cells synergistically accelerated tumour growth due to their activity in complementary oncogenic pathways: the PI3K/AKT and MAPK/ERK pathways, respectively." (PMID 27876799, 2016).
tumor (continued). "Applying these new insights, we improved upon the traditional concepts of ErbB2 targeting by designing and mechanistically dissecting new biparatopic agents that trap ErbB2 in a dimerization-incompetent state thereby entailing the pan-ErbB inhibition in ErbB2-addicted tumours." (PMID 27255951, 2016). "We also provided evidences that the mechanism underlying the synergistic interaction between the two classes of agents is related to the downregulation of EGFR and ErBB2 and to the differential modulation of ErbB3 based on tumor cell phenotype, epithelial vs mesenchymal, induced by the HDACis." (PMID 26862736, 2016). "Thus, none of the therapeutic ErbB2/3-targeting mAbs can fully exploit the addiction to ErbB2 as a tumour's fragile point for therapeutic intervention." (PMID 27255951, 2016). "Finally, we examined ERBB2 expression in GC tumor RNA-seq datasets from The Cancer Genome Atlas (TCGA)." (PMID 26955870, 2016). "Importantly, the “Achilles heel” of the tumor-initiating cells (TIC)/CSC-rich tumorspheres was shown to be the elevated ErbB2 whose expression is ablated by metformin." (PMID 27164115, 2016). "We therefore hypothesized that ERBB2 and ERBB3 activating mutations might be over-represented in ILC harboring atypical features such as high tumor grade or ERBB2 amplification." (PMID 27602491, 2016). "Although either downregulation of EGFR and ErbB2 or increased ErbB3 expression upon treatment with HDACi have been reported before in tumor cells and particularly in NSCLC cell lines, to our knowledge this is the first study reporting these effects in primary cultures." (PMID 26862736, 2016). "Hence, the small-molecule inhibitors appear to not only amplify the activity of low-potency antibodies on ErbB2-overexpressing tumours, but also exert toxicity on cells from tissues with low ErbB2 expression levels, leading inevitably to adverse side effects." (PMID 27255951, 2016). "Targeting this interaction could provide a basis for the development of new anti-cancer drugs, which may help overcome acquired tumor-resistance to ErbB2-targeted drugs." (PMID 27542246, 2016). "However, clinical studies have suggested that erbB2 and MEK signalling are linked via Pak1 (p21-activated kinase), a context that involved tumour cell-matrix interactions and is supported by our 3D data." (PMID 27251376, 2016). "Our previous studies demonstrated that low concentrations of an HSP90 inhibitor, 17AAG, could however promote Trast-induced lysosomal delivery of ErbB2 and produce synergistic anti-tumor killing in vitro." (PMID 26859680, 2016). "By contrast, in ErbB2-addicted tumours induction of apoptosis occurs independently of Src status." (PMID 27255951, 2016). "This latter observation could indicate that ErbB2 is involved in tumor angiogenesis of different brain tumors." (PMID 27091344, 2016). "Thus, we propose a novel pathway for ErbB2-activation, which promotes oncogenic transformation, and affects tumor growth and disease progression." (PMID 27542246, 2016). "It isassumed that HA can play a key role in tumor invasion, since there is a directrelation between overexpression of HA and erbB2, which promotes the activationof the erbB2-dependent signaling pathway and indicates the importance of HA forthe manifestation of an invasive cell phenotype." (PMID 27795844, 2016). "In addition, the tumor suppressor miR-125a, which targets ERBB2 (erb-b2 receptor tyrosine kinase 2), and miR-129, which targets CDK6 (cyclin-dependent kinase 6), are also involved in anti-proliferative and pro-apoptotic functions." (PMID 27322246, 2016).
tumor (continued). "In this scenario, NRG-1 may advance tumor growth and/or promote tumor resistance during treatment with anti-ErbB2 therapies." (PMID 27596216, 2016). "The prognostic value of a pCR may be greatest in aggressive tumor subtypes, including ERBB2-positive tumors." (PMID 27576528, 2016). "We divided the GC tumor datasets into two groups according to high vs. low ERBB2 expression." (PMID 26955870, 2016). "Thus, the possibility to induce tumour cell death by incapacitating critical nodes of the oncogenic network provides a strong rationale for targeting the ErbB2/3 oncogenic unit and the downstream signalling in ErbB2-addicted tumours." (PMID 27255951, 2016). "A recent study reported ERBB2 amplification during extravillous trophoblast differentiation and indicated a similar amplification event in the persistent gestational trophoblastic disease, which is a trophoblast-originating tumor." (PMID 26760505, 2016). "The somatic mutation profile of a tumour may contribute to this; for example, tumours harbouring or acquiring driver mutations in ESR1 or ERBB2 or amplifications at 8p12 (FGFR1) or 11q13 (CCND1) may be less responsive to targeted endocrine therapy." (PMID 25849106, 2015). "Two studies that used expression profiling of selected genes in archived formalin-fixed, paraffin-embedded (FFPE) tumor blocks support the significance of ERBB2 mRNA expression in predicting trastuzumab benefit, and evidence for the predictive value of tumor-infiltrating lymphocytes is emerging." (PMID 26334217, 2015). "For ERBB2, this corresponds to detection of low-level amplification in patients with ~12% tumor fraction or detection of high-level amplification in patients with ≤6% tumor fraction." (PMID 26474073, 2015). "As illustrated in these figures, microscopically normal cells can contain two to five copies of ERBB2, while tumor cells from the same paraffin-embedded tissue section could contain up to 30 ERRB2 gene copies." (PMID 26430163, 2015). "Three tumours contained mutations in ERBB2/RAS/RAF/MEK pathway members or regulators: an ARAF mutation in combination with a NCK1 mutation, a PAK1 mutation in combination with a NF1 mutation, and an ERBB2 mutation in combination with a TSC1 mutation." (PMID 26506417, 2015). "In this report, mouse tumor tissues overexpressing ErbB2 showed nuclear localization of β-catenin." (PMID 26268703, 2015). "When multivariate analysis was corrected by the covariables tumor size, histological grade, lymph nodes, hormone receptors, ErbB2, therapy (adjuvant chemotherapy and hormones), the best predictive markers for the presence of BrM were FN14 (p < 0.0001) followed by GRP94 (p = 0.0017)." (PMID 26497551, 2015). "We found a weak negative correlation between ErbB2 RNA levels and tumor latency, and positive associations with the number of tumors and metastases." (PMID 25853295, 2015). "Consistent with this situation, the first-order correlations between ErbB2-IR and either the Gleason score or % of core that was tumour associated controlling for the tumour Ki67 index were not significant." (PMID 25215939, 2014). "The association with the Ki67 is consistent with a large study using samples obtained at radical prostectomy, where the average Ki67 labelling index was higher for the 388 ErbB2-positive tumour samples than for the 1940 ErbB2-negative samples (6.1 vs. 4.3, respectively,)." (PMID 25215939, 2014). "Tumour stages for patients with different tumour epithelial ERBb2-AR and AR-IR scores." (PMID 25215939, 2014). "It is not clear whether same mechanisms are utilized to simultaneously upregulate both erbB2 and erbB3, or whether tumor cells first overexpress one receptor which subsequently enhances expression of the other receptor." (PMID 24886126, 2014). "It is possible that inhibition of the ErbB2 signaling axis may sensitize tumor cells to the DNA damaging effects of PUVA therapy by inhibiting P3K-Akt regulated DNA damage repair enzymes." (PMID 24551203, 2014).
tumor (continued). "Importantly, the high-level ERBB2 amplification was only noted through our plasma-Seq analysis, as from the primary tumor only small samples from bioptic procedures insufficient for a detailed analysis of the tumor genome were available." (PMID 24676216, 2014). "The authors also observed that levels of ErbB2, pErbB2, and cyclin D1 increased in a time-dependent manner in the mammary glands in BRCA1-deficient mice, and CDDO-Me inhibited the constitutive phosphorylation of ErbB2 in tumor tissues from these mice." (PMID 24552536, 2014). "In humans, erbB2-positive tumours tend to metastasize early and often disseminate into the brain." (PMID 23963762, 2014). "Moreover, of the 10 patients with ERBB2 changes in either the primary tumor or the CTCs, eight patients (80%) displayed disparate ERBB2 amplification states." (PMID 25358515, 2014). "Active immunization targeting ErbB2 might block tumor growth more proficiently than passive immunotherapy thanks to the activation of a persistent memory immune response." (PMID 24886178, 2014). "BIBW 2992 is an irreversible ErbB-family (EGFR/ErbB2/ErbB4) inhibitor, which in previous experiments demonstrated a significant prolongation of tumour growth time in a combined setting with single dose irradiation in FaDu tumour xenografts." (PMID 25444177, 2014). "In theory, it is possible that although the AUC for tumour ErbB2-IR is modest, it could contribute to a combination of markers with useful prognostic value." (PMID 25215939, 2014). "Thus, 9% of cases with tumour stage 3 had low expression levels of both AR-IR and ErbB2-IR, whilst 73% of the cases had high expression levels of both parameters." (PMID 25215939, 2014). "However, in our material, cases with levels of both tumour ErbB2-IR and AR-IR above the median were less common in patients with stage 3 tumours (n = 58) than for stage 2 tumours (n = 82)." (PMID 25215939, 2014). "In tumor cells, integrin β4 can relocate from hemiodesmosomes to the leading edge of migrating cells where it is involved in the signaling of many receptor tyrosine kinases, including ErbB2, ErbB3, EGFR and Met." (PMID 24885350, 2014). "Androgen removal affects ErbB2 expression in tumour cell lines and in xenograft models." (PMID 25215939, 2014). "In ErbB-2-overexpressing tumours, ErbB-2 signals through Plexin-B1 and RhoA to promote metastasis." (PMID 25137062, 2014). "Anti-tumor efficacy of the molecules was tested in several mouse models of human cancer including BT474 and SKOV3 (ovarian) both of which contain PIK3CA mutations (H1047R or K111N) and amplification of ERBB2 rendering the AKT pathway hyperactive." (PMID 24978597, 2014). "Interestingly, miR-125b is heavily downregulated in several of these ERBB2/3-driven tumor entities, allowing for further ERBB2/3 upregulation, thereby promoting malignant transformation." (PMID 24774301, 2014). "Furthermore, a modified psoralen derivative that lacks the ability to crosslink DNA maintained its ability to block ErbB2 signaling and induce tumor cell apoptosis." (PMID 24551203, 2014). "Furthermore, PUVA can reverse therapeutic resistance to lapatinib and other ErbB2 targeted therapies, including resistance mediated via expression of a phosphorylated, truncated form of ErbB2 (p85ErbB2) that is preferentially expressed in tumor cell nuclei." (PMID 24551203, 2014). "However, this is entirely reasonable in ordinal regression models when the variable in question has a large number of categories (there are 22 different tumour ErbB2 scores ranging from 1 to 4 in the database)." (PMID 25215939, 2014). "ERBB2/HER2/neu (HER2) positive tumours are treated with the monoclonal antibody herceptin." (PMID 23307470, 2013). "This tumor was the only one sequenced harboring a HER2/ERBB2 amplification." (PMID 24098698, 2013). "Furthermore, Trastuzumab treatment was accompanied by an inhibition of ErbB2 triggered signalling in polyQ-huntingtin-expressing tumour cells." (PMID 23300147, 2013).